U2AF1 (U2 small nuclear RNA auxiliary factor 1)
Diseases named in the same sentence as U2AF1 in open-access papers (continued):
Sharing a sentence is not in itself a finding about the gene and the disease.
myeloid neoplasm (33 papers, 2012 to 2026). Proliferation of myeloid cells originating from a primitive stem cell. "In this study, we characterized the in vivo consequences of expressing two myeloid neoplasm-associated hotspot mutations in U2AF1 that code for S34F and Q157R substitutions." (PMID 40386435, 2025). "The presence of several genes recurrently mutated in myeloid malignancies, such as U2AF1, IDH2R140Q, IDH1R132H, FLT3D835Y, and DNMT3AR882H, results in immunogenic neoantigens that appear targetable by clonal T-cell receptor (TCR)-based cellular therapies." (PMID 39997326, 2025). "The co-occurrence of U2AF1 and signaling gene mutations also differed across myeloid neoplasms, with NRAS and FLT3 mutations being more common with S34 mutations and CBL, PTPN11 and CSF3R mutations more common with R156/Q157 mutations." (PMID 40386435, 2025). "Mutations in splicing factors, particularly U2AF1, have become prevalent key factors in myeloid malignancies." (PMID 39551864, 2024). "Frequent somatic mutations in splicing factors including SF3B1, SRSF2, and U2AF1 were discovered in myeloid malignancies as well as solid tumors." (PMID 37810965, 2023). "Mutations in U2AF1 have been described in myeloid neoplasms, with variants causing specific alterations in 3′ splice site recognition." (PMID 37735430, 2023). "Here, for the first time, we summarize the research progress of U2AF1 mutations in myeloid malignancies, including the correlations between U2AF1 mutations with clinical and genetic characteristics, prognosis, and the leukemic transformation of patients." (PMID 36139566, 2022). "This review summarizes the biological and clinical implications of the oncogenic role of U2AF1 mutation in myeloid tumors." (PMID 36139566, 2022). "Over the past few decades, the mutation landscape of U2AF1 (most frequently involved S34 and Q157 hotspots) has been drawn in multiple cancers, particularly in myeloid malignancies." (PMID 36139566, 2022). "Our work provides important and comprehensive insights into the development of the U2AF1 mutation as a novel prognostic biomarker and therapeutic target for myeloid malignancies." (PMID 36139566, 2022). "Evaluating the molecular associations between U2AF1 and other gene mutations in patients with myeloid neoplasms can help to understand the biological significance of U2AF1 mutations." (PMID 36139566, 2022). "The high mutation frequency of U2AF1 in myeloid neoplasms, especially in MDS and AML, contributes to abnormal hematopoiesis and cancer progression." (PMID 36139566, 2022). "The effects of U2AF1 mutations on the survival and leukemia transformation of patients with myeloid malignancies remain controversial." (PMID 36139566, 2022). "While overlapping effects of U2AF1 mutations on gene expression and splicing have been observed in both myeloid neoplasms and lung carcinomas, the distribution of mutation hotspots are significantly different between them, as highlighted here." (PMID 31836708, 2019). "When considering recurrent somatic alterations involving splicing factors found in human tumors, U2AF1 S34F mutations are unique in their specific enrichment within both a subset of myeloid malignancies and LUADs35,56,57." (PMID 31836708, 2019). "These were twice combined with additional mutations, including TET2 and SRSF2 mutations in a CMML case, and ASXL1, TET2, and U2AF1 mutations in the disseminated case of an undefined myeloid neoplasm accompanied by HLH (case 10)." (PMID 30084011, 2018). "In this study, we analyzed the frequency and clinical impact of U2AF1 mutations in a cohort of 452 Chinese patients with myeloid neoplasms." (PMID 23029227, 2012).
myeloid neoplasm (continued). "Thus, here, we comprehensively summarize the genetic landscape, clinical relevance, molecular pathogenesis, and therapeutic applications of oncogenic U2AF1 mutations in myeloid malignancies." (PMID 36139566, 2022). "U2AF1 mutations in some patients with clonal cytopenias of undetermined significance may have positive predictive value for the risk of developing myeloid neoplasms." (PMID 36139566, 2022). "Overall, the U2AF1 mutation is stable during the disease progression of myeloid tumors and may be one of the potential biomarkers for risk stratification and monitoring therapy response in patients with myeloid malignancies, especially MDS." (PMID 36139566, 2022). "However, another comprehensive analysis of U2AF1 mutations in 843 patients with myeloid neoplasms holds the view that U2AF1 mutants were only positively correlated with the occurrence of ASXL1 and KIT mutants in MDS/MPN patients, but not in MDS or AML patients." (PMID 36139566, 2022). "U2AF1 mutated hematopoietic cells, primary patient cells, and transgenic mice exhibit increased sensitivity to sudemycin treatment, a compound that regulates pre-mRNA splicing, indicating the potential of sudemycin for myeloid neoplasms patients with U2AF1 mutations." (PMID 36139566, 2022). "Pathogenic variants specific for MDS‐type myeloid neoplasms were found by NGS in the NRAS, U2AF1 and ZRSR2 genes with VAFs of 40%, 24% and 6%, respectively." (PMID 40066790, 2025). "Spliceosome mutations, such as SRSF2, U2AF1, and ZRSR2, are adverse prognostic features typically associated with secondary AML and are relatively common in myeloid neoplasms, making the spliceosome an attractive drug target." (PMID 39997326, 2025). "Mutations in spliceosome genes U2AF1 and SF3B1 have been linked to the expression of oncogenic IRAK4 isoforms in myeloid malignancies." (PMID 38666914, 2024). "The most commonly mutated spliceosome genes in myeloid malignancies, SF3B1, SRSF2, and U2AF1, are also frequently identified in individuals with CHIP." (PMID 38028538, 2023). "In myeloid malignancies such as MDS and AML, spliceosome mutations of SF3B1 or U2AF1 lead to formation of hypermorphic IRAK-4 isoforms (IRAK-4-L) which activate myddosomal signaling promoting cell survival." (PMID 37954584, 2023). "Murine models with conditional heterozygous expression of splicing factor (SF) mutations (SF3B1, U2AF1, SRSF2, ZRSR2) have confirmed the causative effects of RNA splicing dysregulation in the pathogenesis of myeloid malignancies and CLL." (PMID 37463047, 2023). "U2AF1 is a recurrent somatic mutation in the splicing factor, and at a low frequency in AML and MDS, U2AF1 can activate immune pathways and affect myeloid malignancies." (PMID 36799265, 2023). "At the same time, SF3B1 (Splicing Factor 3b Subunit 1), U2AF1 (U2 Small Nuclear RNA Auxiliary Factor 1), NPM1, and FLT3 are rarely mutated in GATA2-mutated myeloid neoplasms." (PMID 35054439, 2021). "According to the cBioPortal database reporting of 4 studies of adult MDS and AML patients, U2AF1 mutations occur in 5% and NPM1 is mutated in 22% of all myeloid malignancy patients." (PMID 33137094, 2020). "U2AF1 mutations altered sequence specificity of pre-mRNA binding and splicing and was an important feature of the pathogenesis of MDS and related myeloid neoplasms." (PMID 30002740, 2018). "U2AF1 constitutes an integral component of the spliceosome, and alterations within the U2AF1 gene represent prevalent genetic aberrations observed across various myeloid neoplasms and several forms of lymphoproliferative disorders." (PMID 39584923, 2024).
myeloid neoplasm (continued). "Isoform modulation of U2AF1S34F target genes H2AFY and STRAP can rescue the erythroid differentiation defects caused by the U2AF1 mutant in MDS cells, suggesting that splicing regulators may be effective against myeloid tumors with the U2AF1 mutation." (PMID 36139566, 2022). "As one of the most common mutations in myeloid neoplasms and an early oncogenic driver of myelodysplasia, a systematic understanding of the U2AF1 mutation is currently lacking." (PMID 36139566, 2022). "In addition, future research should explore the exact molecular mechanisms of U2AF1 mutations in driving leukemogenesis to improve the precision treatment for myeloid malignancies with U2AF1 mutants." (PMID 36139566, 2022). "The identified p.R35L mutation was previously reported in 2 cases of myeloid neoplasms, but to the best of our knowledge, U2AF1 has never been associated with T-ALL prior to this study." (PMID 27602765, 2016). "Furthermore, mutation driver genes SRSF2, U2 small nuclear RNA auxiliary factor 1 (U2AF1), and the epigenetic regulator isocitrate dehydrogenase 1 and 2 (IDH1/IDH2) are recurrently mutated in numerous myeloid neoplasms and are associated with unfavorable clinical prognosis." (PMID 38616283, 2024). "While the observation that U2AF1S34F and U2AF1Q157P are the most frequent U2AF1 MT in myeloid neoplasms is not new, our study is the first to demonstrate their unique co-mutational spectrum and differential prognostic effect." (PMID 37735430, 2023).
leukemia (17 papers, 2016 to 2024). A malignant (clonal) hematologic disorder, involving hematopoietic stem cells and characterized by the presence of primitive or atypical myeloid or lymphoid cells in the bone marrow and the blood. "Oncogenic mutations in splicing regulators, including SF3B1 and U2AF1, are therapeutic liabilities in leukemias and lymphomas,56." (PMID 38114498, 2023). "These alterations help to understand the molecular mechanisms of the U2AF1 mutation in leukemia pathogenesis and develop novel therapeutic targets." (PMID 36139566, 2022). "Mutations in U2AF1 in leukemia have been shown to impact splicing of hundreds of genes and have widespread consequences." (PMID 33087122, 2020). "Although prior studies have reported that mutations in SF3B1, SRSF2, and U2AF1 cause global R-loop augmentation, to our knowledge, no studies thus far have assessed cen-R-loop levels or their roles in the pathogenesis of SF mutant leukemia." (PMID 37463047, 2023). "However, more studies have shown that de novo MDS patients with recurrent U2AF1 mutations (especially S34) have an increased risk to progress to sAML and shorter time-to-leukemia transformation." (PMID 36139566, 2022). "However, there is insufficient evidence that the U2AF1 mutation can replace these well-accepted predictors of leukemia transformation." (PMID 36139566, 2022). "PRPF8 is the only U5 snRNP protein where recurrent somatic mutations have been linked to cancer, joining the ranks of spliceosome factors such as U2AF1 and SF3B1 as frequently mutated in certain types of human cancers, in particular leukemias." (PMID 33584830, 2021). "There are four studies reporting that the presence of U2AF1 mutations has no significant impact on the overall survival (OS) or leukemia-free survival in MDS patients." (PMID 36139566, 2022). "U2AF1 p.R35L was shown to induce aberrant splicing of downstream target genes, and shRNA knockdown of MED12 and USP9X was shown to confer resistance to apoptosis following T-ALL relevant chemotherapy drug treatment in Jurkat leukemia cells." (PMID 27602765, 2016).
Myelodysplasia (15 papers, 2017 to 2025). Clonal hematopoietic stem cell disorders characterized by dysplasia (ineffective production) in one or more hematopoietic cell lineages, leading to anemia and cytopenia. "At diagnosis, our patient had a deletion of 11q23 involving monosomic KMT2A loss without rearrangement, which is considered an intermediate-risk feature, and U2AF1 mutation, which is considered an adverse-risk myelodysplasia-related gene mutation." (PMID 41008781, 2025). "For example, mutations in the splicing factor U2 Small Nuclear RNA Auxiliary Factor 1 (U2AF1), affects pre-mRNA splicing and contributes to the progression of cancer such as myelodysplasia (MDS); even with a single mutation such as S34F, which affects hundreds of mRNAs." (PMID 33923168, 2021). "In particular, the adverse-risk group has been expanded to include seven additional mutations: BCOR, EZH2, SF3B1, SRSF2, STAG2, U2AF1, and ZRSR2—together with ASXL1 and RUNX1 (already included in ELN 2017)—forming the “myelodysplasia-related” (MR) gene group." (PMID 41464583, 2025). "Only 5 were assigned to the adverse group because of myelodysplasia-related mutations (RUNX1, n = 2; BCOR, n = 1; SF3B1, n = 1; U2AF1, n = 1)." (PMID 37085611, 2023). "The U2AF1 mutation is specifically associated with trilineage morphologic dysplasia (erythroid, myeloid, and megakaryocytic) in AML with myelodysplasia-related changes." (PMID 36139566, 2022). "The presence of mutations in at least one gene associated with myelodysplasia (i.e., SRSF2, SF3B1, U2AF1, ZRSR2, ASXL1, EZH2, BCOR, or STAG2) was significantly more frequent in older patients." (PMID 35805006, 2022). "This was supported by in vitro experiment data, the flanking sequence of the cassette exon that promotes binding of U2AF1 S34 mutant protein, and the mutational landscape of myelodysplasia in which EZH2 and U2AF1 S34 mutations were mutually exclusive." (PMID 30194306, 2018). "Seventy-nine patients, or 45% of all re-classified patients, were moved from ELN-2017 favorable (n = 11) or intermediate (n = 68) to ELN-2022 adverse risk based on the inclusion of additional myelodysplasia-related (MR) mutations (BCOR, EZH2, SF3B1, SRSF2, STAG2, U2AF1, ZRSR2) as poor-risk markers." (PMID 37041198, 2023). "Males had a higher frequency of mutations in genes of the spliceosome complex (SF3B1, SRSF2, U2AF1 or ZRSR2) (19.1% vs. 5.7% in females; P = 0.002) and the nine myelodysplasia-related genes (31.6% vs. 17.9% in females; P = 0.015)." (PMID 38890297, 2024).
chronic myelomonocytic leukemia (12 papers, 2019 to 2025). A myelodysplastic/myeloproliferative neoplasm which is characterized by persistent monocytosis, absence of a Philadelphia chromosome and BCR/ABL fusion gene, fewer than 20 percent blasts in the bone marrow and blood, myelodysplasia, and absence of PDGFRA or PDGFRB rearrangement. "Mutations in SF3B1, SRSF2, and U2AF1 have been associated with specific disease subtypes with SF3B1 being mostly mutated in MDS-RS, SRSF2 occurring mostly in chronic myelomonocytic leukemia (CMML), and U2AF1 in secondary AML." (PMID 31766606, 2019). "Finally, for comparison, in the analysed articles, around 33% of chronic myelomonocytic leukemia (CMML) patients harbored SRSF2 mutations; 8% U2AF1 mutations, 9% ZRSR2 mutations and 5%, SF3B1 mutations." (PMID 32784800, 2020).
lung adenocarcinoma (12 papers, 2014 to 2023). A carcinoma that arises from the lung and is characterized by the presence of malignant glandular epithelial cells. "Previous cancer genomic studies across lung adenocarcinoma (ADC) patients have revealed recurrent mutations in the splicing factor U2AF1." (PMID 37487637, 2023). "The functional role of U2AF1 mutations in lung adenocarcinomas (LUADs) remains incompletely understood." (PMID 31836708, 2019). "In total, 35% of the U2AF1 S34F/Y-associated splicing changes seen in lung adenocarcinoma or AML are supported by splicing changes caused by U2AF1 S34F expression in HeLa cells." (PMID 24498085, 2014). "U2AF1 S34F mutations were found in eight lung adenocarcinomas (4%), four AML samples (2%), two endometrial carcinomas (1%), and one bladder cancer sample (1%)." (PMID 24498085, 2014). "We did not observe a significant upregulation in expression of NMD factors associated with U2AF1 mutation in lung adenocarcinoma or AML." (PMID 24498085, 2014). "We found a significant overlap of 30 altered splicing events that were associated with U2AF1 S34F/Y mutations in both lung adenocarcinoma and AML (Fisher's exact test p<2.2e-16)." (PMID 24498085, 2014). "U2AF1 mutations co-occur with mutations in known driver oncogenes in lung adenocarcinoma and it is yet unclear if these mutations are oncogenically transforming." (PMID 24498085, 2014). "To identify potential downstream biological consequences of U2AF1 mutation, we performed a Gene Set Enrichment Analysis (GSEA) to identify gene sets positively correlated with the U2AF1 S34F/Y mutation in lung adenocarcinoma and in AML." (PMID 24498085, 2014). "U2AF1 has been reported to have significant hotspot mutations at amino acid position 34 in myelodysplastic syndromes, lung adenocarcinomas, and AML." (PMID 24498085, 2014). "Comparing U2AF1 S34F/Y mutation with U2AF1 wild-type samples (some with mutations in other splicing factors) yielded similar results in lung adenocarcinoma (TCGA, submitted) and AML." (PMID 24498085, 2014). "U2AF1 is one of the most recurrently mutated splicing factors in lung adenocarcinoma and has been shown to cause transcriptome-wide pre-mRNA splicing alterations; however, the full-length altered mRNA isoforms associated with the mutation are largely unknown." (PMID 37487637, 2023). "Importantly, it has also been shown that the disruptions of U2AF1 expression that occur in patients with lung adenocarcinoma also cause changes in SMN2 splicing, emphasizing that variations of U2AF1 and SMN2 splicing also occur in humans in vivo." (PMID 33438800, 2020). "Among these factors, only U2AF1 is known to be recurrently mutated in lung adenocarcinomas (LUADs)." (PMID 27776121, 2016). "For example, in lung adenocarcinoma, alterations in splicing driven by U2AF1 induce cell cycle dysregulation and mitotic stress." (PMID 31969990, 2020). "The authors report a co-occurrence of the U2AF1 S34F splicing factor mutation and ROS1 translocations in lung adenocarcinomas and profile effects of S34F on transcriptome-wide RNA binding." (PMID 31836708, 2019). "U2AF1 was reported to be significantly mutated in both lung adenocarcinomas and AML; however, not significantly mutated in endometrial carcinomas, most likely due to the low frequency within this cancer type." (PMID 24498085, 2014).